GSK3B (glycogen synthase kinase 3 beta)
Diseases named in the same sentence as GSK3B in open-access papers (continued):
Sharing a sentence is not in itself a finding about the gene and the disease.
tauopathy (continued). "Here, we examined the potential of APPsα to regulate two major Tau kinases, GSK3β and CDK5 in THY-Tau22 mice, a widely used mouse model of tauopathy." (PMID 36779015, 2023). "Our results are consistent with a previous report using a D. melanogaster model of tauopathy, demonstrating the activity of PAR-1 as a prerequisite for the activity of GSK3β." (PMID 36232909, 2022). "MiR-132 provides neuroprotection for tauopathies via regulating the tau modifiers acetyltransferase EP300, kinase GSK3β, RNA-binding protein Rbfox1 and proteases Calpain2 and Caspases 3/7." (PMID 30881384, 2019). "Researchers studying the inverse effects of GSK-3β have determined that GSK-3β inhibitors, such as Lithium Carbonate (Li2CO3), can inhibit the tauopathy in AD." (PMID 31588368, 2019). "GSK-3β and CDK5 regulate the activation of tau phosphorylation and this phosphorylation leads to tauopathy." (PMID 31588368, 2019). "Several studies have highlighted the role of GSK3β-mediated tau phosphorylation in UPR activation and tauopathy progression." (PMID 28386764, 2017). "3xTgAD and transgenic p25 mice treated with diaminothiazoles can reduce tauopathy and improve cognitive function by both CDK5 and GSK3β inhibition." (PMID 25309427, 2014). "Since both protein kinases are dysregulated in several neurodegenerative diseases (e.g., tauopathies) and in neuropathic pain, the investigated extract could show therapeutic effects in such disorders through dual inhibition of CDK5 and GSK-3β." (PMID 38732407, 2024). "Moreover, epibrassinolides increased GSK‐3β phosphorylation and decreased CDK5 expression in tauopathy model PC12 cells, suggesting that epibrassinolides have neuroprotective effects in vitro and in C. elegans model by inhibiting GSK‐3β Ser9 phosphorylation." (PMID 39129397, 2024). "In summary, we showed that a single high-energy head impact induces chronic white matter injury and altered GSK-3β activity without an apparent change in post-injury tauopathy in rTg4510 mice." (PMID 37298388, 2023). "Further, GSK3β activation was found to be regulated in a PI3K/Akt-dependent and -independent manner, ultimately leading to an increased Tau phosphorylation, a pathological feature of AD and other tauopathies." (PMID 33562061, 2021). "GSK3β is ubiquitously active and is a critical effector of PI3 K/AKT cellular signaling which involved in the cellular process such as cell metabolism, cell death, and tauopathy for AD." (PMID 33783931, 2021). "Recently we reported that expression of Nectin-3, an important cell adhesion molecule (CAM) was compromised in the CA1 SLM of two transgenic models for tauopathy, carrying Tau.P301L without or with GSK3β." (PMID 24498342, 2014). "The unexpected negative contribution of GSK3β in biGT mice to the levels of phospho-epitopes and to the delayed tauopathy, would be substantiated by biochemical examination, which is evidently not possible for the tiny sub-regions of the hippocampus." (PMID 24498342, 2014). "In translational terms, these data do not warrant the search for specific GSK3β inhibitors that spare GSK3α, as a therapeutic means for tauopathies in which GSK3 are thought to contribute." (PMID 23705847, 2013). "These and other findings might eventually provide critical guidance in the development of better treatments of tauopathies, some of which could be targeted at upregulating NR2A-mediated reduction of GSK3β activity by PKC isoforms." (PMID 24349798, 2013). "Atg7 cKO in mouse forebrain neurons led to an age-dependent neurodegeneration with ubiquitin/p62-positive and phospho-tau/GSK3β inclusions, but not the full pathological features of NFTs in tauopathy." (PMID 22998728, 2012). "Furthermore, PKR initially facilitated tau hyperphosphorylation, which is independent of PKR-mediated downstream activation of GSK-3β or neuroinflammation in AD and other tauopathies." (PMID 36172481, 2022).
tauopathy (continued). "Thus, DMF activation of NRF2 through two distinct proteolytic pathways, a KEAP1 dependent one and the other mediated by GSK-3β phosphorylation, makes this compound a promising therapy for neurodegenerative diseases as tauopathies, where either KEAP1 or GSK-3β activities are altered." (PMID 32756501, 2020). "The combined outcome illustrated not only the stronger effect of the early stages of beginning tauopathy on the CNP2 isoform, but also the synergistic impact of GSK3β with Tau.P301L on axonal myelination in the hippocampus of the bigenic biGT mice, with inherently higher GSK3β activity." (PMID 24498342, 2014). "Among protein kinases, GSK-3β (a proline-directed protein kinases) and CDK5 (a non-PDPK non-proline-directed protein kinase) are probably the two most important kinases in tauopathy." (PMID 30333786, 2018). "In contrast, unlike GSK-3β and CDK5, a series of protein phosphatases (PP-2A, PP-2B, and PP-1) can dephosphorylate protein tau in vitro and in vivo, which may act to protect against tauopathy." (PMID 30333786, 2018).
bipolar disorder (82 papers, 2007 to 2026). A disorder of the brain that causes unusual shifts in mood, energy, activity levels and the ability to carry out day-to-day tasks. "Evidence from a genetic study reported significant associations between single nucleotide polymorphisms in GSK3β and impulsivity in bipolar disorder patients." (PMID 41276636, 2025). "In a study of GSK-3β polymorphisms, rs6438552, rs2199503, and rs334558 are considered to be involved in the treatment of patients with bipolar disorder." (PMID 33658947, 2020). "Interaction between polymorphisms affecting cortical expression of the FXR1 and GSK3B genes have been shown to regulate mood-related behavioral dimensions in healthy humans and patients with bipolar disorder." (PMID 29706865, 2018). "Moreover, GSK3β inhibits neuronal transport by phosphorylating the kinesin light/heavy chains in an ANK3 deficiency model of bipolar disorder." (PMID 36504683, 2022). "However, further study is required to clarify the underlying mechanisms of overlapping proinflammatory cytokines and GSK-3β dysregulation in bipolar disorder and the atopic comorbidities in susceptibility to ischemic stroke." (PMID 30114239, 2018). "Therefore, although we could not find a significant association between the GSK-3β gene and bipolar disorder and dementia in this GWAS review, rs334558 of the GSK-3β gene is associated with bipolar disorder and dementia." (PMID 39228919, 2024). "Our findings may shed new light on the understanding of the cellular and molecular mechanisms underlying therapeutic actions of lithium in Bipolar Disorder, and suggest that specific targeting of GSK3β in particular may offer novel treatment solutions for BPD patients." (PMID 22428012, 2012). "Lithium, used in bipolar disorder, inhibits GSK-3β and promotes autophagy and mitochondrial stability, with emerging evidence suggesting neuroprotective and potential lifespan-extending effects." (PMID 40666427, 2025). "The aim was to search for consistent differences in GSK3α and GSK3β or of their phosphorylated forms in samples of peripheral blood from patients with unipolar and bipolar depression." (PMID 37807001, 2023). "The NGF, FGF2, NT-3, BDNF, IL-1-β, and dopamine factors also indirectly impact the action of GSK-3β in bipolar disorder." (PMID 37569304, 2023). "The MetaCore analysis suggested that regulating GSK-3β in bipolar disorder was closely correlated with the DBNDD1 gene and its co-expressed genes in the progression of PCa." (PMID 37569304, 2023). "Lithium is the best-known GSK3β inhibitor and has been prescribed as the first line regimen to treat bipolar affective disorders." (PMID 36795689, 2023). "Regulation of glycogen synthase kinase (GSK)-3β in bipolar disorder and ATP/ITP/GTP/XTP/TTP/CTP/UTP metabolic pathways was closely correlated with the DBNDD1 gene and its co-expressed genes in PCa." (PMID 37569304, 2023). "In this line, one of the most studied GSK3β inhibitors and already used in humans for the treatment of bipolar disorder, lithium, also acts indirectly by enhancing the serine phosphorylation of GSK3β." (PMID 35281935, 2022). "Lithium, an FDA approved mood stabilizer, is the best-known GSK3β inhibitor and has been safely used for over half a century as the first line regimen to treat bipolar affective disorders." (PMID 34195206, 2021). "Lithium is a GSK3β inhibitor that has been used for a long time in the treatment of patients with bipolar disorder." (PMID 32850361, 2020). "Lithium is a conventional treatment for bipolar disorder, which exerts a neuroprotective role in various diseases by inhibiting glycogen synthase kinase‐3β (GSK‐3β) in the brain and spinal cord." (PMID 31867790, 2020). "Lithium ion (Li+), an inhibitor of GSK3β, acts on GSK3β directly by competition with magnesium ion in the ATP binding pocket and has already been used for the treatment of bipolar disorders." (PMID 33192176, 2020).
bipolar disorder (continued). "An additional clue in this puzzle is that lithium, which acts upon this pathway and inhibits GSK3B, modulates circadian rhythms in patients with bipolar disorder." (PMID 33193575, 2020). "Lithium chloride (LiCl) is a widely used inhibitor of GSK-3β, and it is also the main drug for the treatment of bipolar disorder." (PMID 33354162, 2020). "Lithium chloride, a psychiatric drug widely used to treat bipolar affective disorder, remarkably inhibits GSK-3β." (PMID 30834157, 2019). "Transgenic mice with GSK-3β overexpression show increased locomotor activity as seen in the manic phase of bipolar disorder." (PMID 31191636, 2019). "Li2CO3 (Lithium carbonate, GSK-3β inhibitor) has been prescribed against manic and bipolar disorders." (PMID 28190217, 2017). "HINT1−/− mice show little phosphorylation at this GSK3β residue, and decreases in the levels of P-S9 GSK3β are correlated with the predominance of mania/hypomania in BPD patients." (PMID 28240305, 2017). "Lithium, a glycogen synthase kinase 3β (GSK3β) inhibitor, is widely used in the treatment of mood disorders, managing both bipolar disorder and unipolar depression." (PMID 28912499, 2017). "Gsk-3β heterozygous (+/-) mice display behaviors that resemble wild type (WT) mice treated with lithium, a drug that is used to treat bipolar disorder, demonstrating that disruption of Wnt signaling leads to behavioral abnormalities." (PMID 27980692, 2016). "As the mainstay of therapy for bipolar affective disorder in the past fifty years, lithium, a typical inhibitor of GSK3β, usually needs to be used at the psychiatric high dose for a long time (usually >10 years)." (PMID 26567873, 2015). "LiCl has been used for decades for the treatment of bipolar disorder by increasing β-catenin signaling through the inhibition of GSK-3β." (PMID 24396427, 2014). "Recent literature suggests that valproate, a diffusely prescribed drug in the treatment of epilepsy and bipolar disorder, can inhibit glycogen synthase kinase-3β (GSK-3β) activity and has cytoprotective effects in neuronal cells and HepG2 cells." (PMID 24884462, 2014). "GSK3β was proposed as a therapeutic target based on the treatment of bipolar disorder with lithium salts, but this however seriously suffers from limited effectiveness, narrow therapeutic window and side-effects." (PMID 23705847, 2013). "Among the prevailing models for bipolar disorder are overexpression of glycogen synthase kinase 3 beta (GSK3 beta) and clock mutant." (PMID 22412961, 2012). "Currently, two major targets of lithium are suggested responsible for the actions of lithium on bipolar disorder and other CNS diseases: inositol depletion and glycogen synthase kinase 3β (GSK-3β) inhibition." (PMID 21711903, 2011). "Since the effects of TAAR1 agonists on bipolar disorder may arise from biased regulation of GSK3β pathways, it would be insightful to investigate whether biased TAAR1 agonists could yield different behavioral outcomes in subsequent studies." (PMID 40351432, 2025). "Given the role of TAAR1 in GSK3β regulation, it is reasonable to hypothesize that TAAR1 agonists may influence the progression of bipolar disorder by modulating GSK3β signaling pathways." (PMID 40351432, 2025). "To test this hypothesis, we set out to treat Dyrk1a-KI mice with lithium, bipolar disorder medication known to exert pleiotropic neurodevelopmental, neuroprotective, and neuro-synaptic effects through multiple mechanisms, including GSK3β inhibition." (PMID 39633007, 2025). "Lithium’s inhibition of GSK3β leads to stabilizing circadian rhythms, which may also contribute to its mood-stabilizing effects in bipolar disorder." (PMID 39703389, 2024). "Lithium, used to treat bipolar disorder, inhibits the activity of the paralog of this gene (GSK3B)." (PMID 37881554, 2023).
bipolar disorder (continued). "Biochemically, AKAP11 interacts with protein kinase A (PKA), a protein that is involved in a variety of biological processes including neuronal plasticity, and with glycogen synthase kinase 3 beta (GSK3β), one of the targets of lithium, a mainstay therapy for bipolar disorder." (PMID 36914641, 2023). "This probably explains why few rare and no common variants of GSK3A or GSK3B genes have been associated with enhanced risk for bipolar disorder." (PMID 36504683, 2022). "Dysfunction of the KCNQ2/GSK3β/PP2A-Bγ regulation pathway, and its balance, can explain changes in neuronal excitability that underline the manic and depressive episodes occurring in mood disorders (e.g., bipolar affective disorder)." (PMID 35457230, 2022). "Lithium, a GSK3β inhibitor, has been used for decades for the treatment of bipolar disorder." (PMID 32850361, 2020). "Mood stabilizers such as lithium and valproate, both commonly used in the treatment of bipolar disorder, modulate circadian rhythms via inhibition of glycogen-synthase-kinase-3-beta (GSK3Beta), which phosphorylates the cycle length determining PER clock gene products." (PMID 32718072, 2020). "Previous studies have proposed that abnormal expression, activity, and signaling systems connected to GSK-3β contributed to the pathophysiology of bipolar disorder, and may influence the atopic inflammatory response." (PMID 30114239, 2018). "In addition, GSK-3β, a kinase involved in Wnt signaling, is used as a marker in neuropsychiatric disorders and is targeted by mood-stabilizing drugs such as lithium for bipolar disorder." (PMID 30200269, 2018). "However, the involvement of Ras-controlled GSK-3β expression and its mechanism of regulation in the pathophysiology of bipolar disorder still remain to be investigated." (PMID 28649228, 2017). "Additionally, lithium is a well-known treatment for bipolar disorder, and one of its main activities is inhibition of GSK-3β, which positively stimulates the canonical Wnt pathway." (PMID 27980692, 2016). "More and more studies suggest that inhibition of GSK-3β may be a more relevant target for the pathophysiology of bipolar disorder and the therapeutic action of lithium." (PMID 21711903, 2011). "mTOR may also serve as a convergence point between the acute antidepressant effects of ketamine and the longer-term prophylactic effects of lithium in bipolar disorder, since a key mechanism of the latter involves GSK3β inhibition, an upstream regulator of mTOR activity." (PMID 41304907, 2025). "Interestingly, the therapeutic action of lithium, an effective mood stabilizer for bipolar affective disorder, may be related to direct effects on the circadian clock via the inhibition of GSK-3β." (PMID 28649228, 2017). "More importantly, mice with heterozygous loss of GSK-3β genotype exhibit behavioral and molecular changes similar to those induced by lithium treatment, and transgenic mice overexpressing GSK-3β show hyperactivity resembling that observed in the manic phase of bipolar disorders." (PMID 21711903, 2011). "In particular, glycogen synthase kinase-3 beta (GSK-3b), an essential kinase involved in cell metabolism and survival, has been identified as having significant effects on neuronal plasticity in bipolar disorder patients." (PMID 34758769, 2021). "Initially, NRF2 activation via GSK-3β inhibition was demonstrated for LiCl, a GSK-3β inhibitor used for the treatment of bipolar disorder and compound TDZD-8, which is able to increased HO-1 expression." (PMID 32545924, 2020). "Lithium, a common medication for bipolar disorder, inhibits GSK3 via Mg+ competition and increased Ser21 (GSK3α) or Ser9 (GSK3β) phosphorylation, leading to enhanced myoblast fusion and myogenic differentiation." (PMID 31671858, 2019).
bipolar disorder (continued). "Among the many selective inhibitors of GSK3β, lithium is the first-generation inhibitor and has been safely used for over a half century as the FDA approved first line mood stabilizer for the treatment of bipolar affective disorders." (PMID 31349118, 2019). "Of course, GSK-3β has many downstream signaling targets, one of which is the Wnt signaling pathway; demonstrating that modulation of GSK-3β activity can have therapeutic effects beyond the treatment of bipolar disorder." (PMID 27980692, 2016). "Although characterization of small molecule inhibitors of GSK-3β is still underway, safety issues have not been reported at least for lithium chloride which is widely used by patients to treat bipolar disorder." (PMID 17786208, 2007). "In a paradoxical sleep deprivation model of mania, lithium was able to reverse behavioral alterations, and bipolar disorder patients that do not respond to lithium treatment have significantly increased activity of GSK3β and decreased expression of circadian clock genes." (PMID 36504683, 2022). "Furthermore, GSK3β activation in response to oxidative stress phosphorylates and induces the degradation of CRMP-2, a cytoskeleton regulator involved in lithium response in bipolar disorder patients, and results in axonal degeneration and neuronal death." (PMID 30285728, 2018). "Furthermore, human SNPs affecting the expression of GSK3B and FXR1 genes in the human prefrontal cortex were shown to interact and affect emotional stability in controls, negative symptoms and antipsychotic drug responsiveness in schizophrenia, as well as symptom severity in bipolar disorder." (PMID 36504683, 2022).